MTOR (mechanistic target of rapamycin kinase)
Diseases named in the same sentence as MTOR in open-access papers (continued):
Sharing a sentence is not in itself a finding about the gene and the disease.
tuberous sclerosis (continued). "The mTOR signaling is involved in highly epileptogenic diseases, including tuberous sclerosis complex (TSC), and it is a reasonable target for antiepileptic intervention." (PMID 37221133, 2023). "Constitutive activation of the mTOR pathway, as observed in Tuberous Sclerosis Complex (TSC), leads to glial dysfunction and subsequent epileptogenesis." (PMID 38089143, 2023). "Furthermore, mTOR inhibitors significantly reduced tumor volume in tuberous sclerosis." (PMID 35300603, 2022). "The purpose of our study is to expand the knowledge regarding intrinsic reproductive dysfunction in females with TSC and to explore the impact of mTOR inhibitors (mTORi) on menstrual irregularity in the Tuberous Sclerosis Complex (TSC) community." (PMID 36303615, 2022). "Hyperactivation of mammalian target of rapamycin (mTOR) is essential in thepathogenesis of tuberous sclerosis complex (TSC) and can serve as a therapeutictarget." (PMID 35246210, 2022). "The histopathology of FCD II is quite similar to that of the cortical tubers in patients with tuberous sclerosis complex (TSC), another disorder related to mTOR pathway dysregulation." (PMID 35626279, 2022). "Defects in pigmentation linked to autophagy dysfunction characterize the tuberous sclerosis complex, an autosomal dominant disorder resulting from a pathogenic variant of TSC1 or TSC2 genes, which are responsible for the constitutive activation of the negative regulator for autophagy-mTOR." (PMID 36230960, 2022). "Tuberous sclerosis complex (TSC) is a hereditary condition related to the mTOR pathway, which is a benign tumor that affects several organs, including the heart, brain, lungs, skin, eyes and kidneys." (PMID 34832914, 2021). "Renal anomalies usuallyfound in tuberous sclerosis complex (TSC) (angiomyolipomas and renal cysts) wereabsent in patients with mosaic MTOR pathogenicvariants." (PMID 33833411, 2021). "PI3K/Akt/mTOR signaling in the context of chordoma was first suggested after numerous reports of chordoma tumors in individuals with tuberous sclerosis complex (TSC)." (PMID 34070849, 2021). "Tuberous sclerosis complex (TSC) is a genetic condition characterized by the occurrence of hamartomatous wounds stemming from the dysfunction of the mammalian target of rapamycin (mTOR) pathway." (PMID 32211034, 2020). "Another disease model to study with regards to mTOR complex functioning is tuberous sclerosis (TSC)." (PMID 32341806, 2020). "The treatment of tuberous sclerosis complex (TSC) using mammalian target of rapamycin (mTOR) inhibitors is clinically promising." (PMID 30760308, 2019). "In addition, activated mTOR signals can also contribute to the development of several syndromes with benign tumors composed of architecturally disorganized but well-differentiated cells, such as Cowden’s syndrome, Peutz-Jeghers syndrome and tuberous sclerosis." (PMID 27835987, 2016). "Tuberous sclerosis complex (TSC) is a genetic disease characterized by benign tumor growths in multiple organs and neurological symptoms induced by mTOR hyperfunction." (PMID 27655340, 2016). "Inhibitors of mammalian target of rapamycin (mTOR) are increasingly used as therapy for pediatric patients with tuberous sclerosis complex (TSC)." (PMID 25574245, 2015). "In addition to tuberous sclerosis, however, there is growing evidence that dysregulated mTOR activity may contribute to a wider variety of autism spectrum disorders." (PMID 24379984, 2013). "AMPK activation leads to the suppression of mTOR via the phosphorylation of TSC2, a component of the tuberous sclerosis complex that negatively regulates mTOR activity." (PMID 39940361, 2025). "For example, the pivotal Examining Everolimus in a Study of Tuberous Sclerosis Complex (EXIST-3) trial demonstrated the efficacy of everolimus, a mammalian target of rapamycin (mTOR) inhibitor, in reducing seizure burden among patients with tuberous sclerosis complex (TSC)." (PMID 40486667, 2025).
tuberous sclerosis (continued). "Tuberous sclerosis complex (TSC) is a multisystemic genetic disorder characterized by the development of benign tumors in various organs, stemming from overactivation of the mechanistic target of rapamycin (mTOR) pathway." (PMID 38540392, 2024). "In prevalent causes of hereditary epilepsy such as focal cortical dysplasia (FCD) and tuberous sclerosis complex (TSC), the involvement of the mTOR pathway in epileptogenesis is notably evident." (PMID 40217521, 2023). "Previous studies have suggested that the topical mechanistic target of rapamycin (mTOR) inhibitors may be effective in treating facial angiofibromas in patients with tuberous sclerosis complex (TSC)." (PMID 35453576, 2022). "Facial angiofibroma is the most predominant cutaneous manifestation of tuberous sclerosis complex (TSC), a rare autosomal dominant genetic disorder impacting the mechanistic target of rapamycin (mTOR)." (PMID 36104799, 2022). "In neurons or Purkinje cell, mTOR complex has a major role in brain development and neuron homeostasis and is severely affected in ASD related syndromes such as the tuberous sclerosis." (PMID 34641964, 2021). "Genetic examples of this phenomenon include tumor growth in Neurofibromatosis 1 and Tuberous Sclerosis, wherein PI3K/Akt and mTOR are upregulated, respectively." (PMID 34215308, 2021). "Interestingly, this is the first study of asiaticoside and asiatic acid against tuberous sclerosis complex (TSC) disease model by targeting mTOR." (PMID 32887218, 2020). "In clinical settings, mTOR inhibitors are effective and FDA approved for treating subependymal giant cell astrocytomas in patients with tuberous sclerosis complex." (PMID 33202963, 2020). "Phosphorylation of TSC2 by Erk promotes dissociation of the tuberous sclerosis complex and attenuates TSC2-mediated inhibition of mTOR in cells." (PMID 30943918, 2019). "Tuberous sclerosis, which is a monogenic disease and causing cystic lesions and angiomyolipomas in kidneys as well as other multisystemic abnormalities, mutations in TSC1 or TSC2 leads hyperactivation of mTOR and mTOR inhibitors might be the first effective treatment for these patients." (PMID 31658846, 2019). "Evidence from several mouse models of ASD-related disorders, including Fragile-X Syndrome (FXS) and Tuberous Sclerosis (TSC) suggest that dysregulation of mTOR and mGluR signaling pathways contribute to deficits in synaptic plasticity and learning and memory." (PMID 30854511, 2017). "Everolimus, a mammalian target of rapamycin (mTOR) inhibitor, has been shown to be effective and safe in the treatment of subependymal giant cell astrocytoma (SEGA) associated with tuberous sclerosis complex (TSC)." (PMID 27502586, 2016). "In the tumor syndrome tuberous sclerosis (TSC) mTOR is indirectly activated by MAPK-mediated phosphorylation of TSC1 and 2 that alleviates inhibition of mTOR." (PMID 25769101, 2015). "Thus, we theorized that BHD syndrome belongs to a larger family of disorders characterized by mTOR deregulation, such as tuberous sclerosis complex (TSC)." (PMID 24910976, 2014). "In the present study, we investigated the potential role of tuberin/mTOR pathway in the regulation of cell fibrosis in AML cells and kidney tumor tissue from tuberous sclerosis complex (TSC) patients." (PMID 23705901, 2013). "In Peutz Jeghers syndrome, Tuberous Sclerosis, and other diseases where PTEN is inactivated, the use of rapamycin as a clinical means to reverse the effect of elevated mTOR activity is an attractive option." (PMID 16404421, 2006). "As there is evidence indicating that mTOR can upregulate RIP3, as demonstrated in enterocolitis and tuberous sclerosis complex, we hypothesized that mTOR may induce astrocyte activation by regulating the expression of RIP3." (PMID 39893345, 2025).
tuberous sclerosis (continued). "Unlike other neurodevelopmental disorders such as tuberous sclerosis, neurofibromatosis type I, and Fragile X syndrome, idiopathic autism is linked to reduced TrkB signaling through the PI3K/Akt/mTOR and Eps8/Rac pathways." (PMID 40149774, 2025). "We observed that mTOR inhibition partially mitigates seizure severity when provided at the appropriate dose, which parallels studies in tuberous sclerosis complex (TSC), where mTOR-targeted therapies reduce but do not eliminate seizures." (PMID 41562862, 2025). "mTOR inhibitors, currently used in the treatment of TSC (tuberous sclerosis complex) and other mTOR-related pathologies, have shown promise in reducing seizure frequency and severity by normalizing synaptic protein synthesis and reducing aberrant neuronal growth." (PMID 39867454, 2024). "Pathogenic somatic mutations in the mechanistic target of rapamycin (mTOR) pathway genes can cause focal cortical dysplasia (FCD) spectrum disorders that are associated with pharmaco-resistant epilepsy, such as FCD Type 2, hemimegalencephaly (HME) and tuberous sclerosis complex (TSC)." (PMID 37250426, 2023). "Tuberous sclerosis TSC is an autosomal-dominant multi-system disorder that results from pathogenic variants in the tumor suppressor genes, TSC1 and TSC2, leading to aberrant activation of the mTOR pathway and often presenting with renal cysts associated with cilia disruption." (PMID 38292052, 2023). "The use of mTOR inhibitors, particularly everolimus, may be considered an important hallmark to treat children (>3 years old) with subependymal giant cell astrocytomas (SEGAs) associated with tuberous sclerosis complex (TSC) and not amenable to surgical treatment." (PMID 36839989, 2023). "The use of mTOR inhibitors in patients with tuberous sclerosis and SEGA also significantly reduces seizure frequency, and therefore, the use of mTOR inhibitors such as everolimus is being considered as part of standard treatment when surgical removal of SEGA is not possible." (PMID 38275375, 2023). "Furthermore, crosstalk between folliculin, mTOR and MiT family transcription factors likely contributes to shared tumorigenesis mechanisms between BHD, tuberous sclerosis and translocation RCC." (PMID 36421797, 2022). "By contrast, the radial glia of the developing mouse brain are less dependent on mTOR signaling and do not develop tubers, arguing for the development of a human cell-based model of tuberous sclerosis." (PMID 36139380, 2022). "Molecular pathology data has provided a rationale for mTOR inhibitor use in patients suffering from PEComa tumors with and without concomitant tuberous sclerosis." (PMID 34442003, 2021). "mTOR inhibitors, namely rapamycin and everolimus, which act by forming a complex with FK506-binding protein-12 (FKBP12) that inhibits mTORC1, have shown clinical benefit in tuberous sclerosis patients." (PMID 33551717, 2020). "In addition, Bissler and colleagues investigated another mTOR inhibitor, sirolimus, treatment for RAML in patients with tuberous sclerosis or sporadic LAM and found a mean reduction in RAML volume of 47% at 12 months." (PMID 29587809, 2018). "Tuberous sclerosis complex is an autosomal dominant disorder characterized by benign tumors arising from the abnormal activation of mTOR signaling in cells lacking TSC1 (hamartin) or TSC2 (tuberin) activity." (PMID 29343513, 2018). "Contrary to disruptions seen in Fragile X syndrome, tuberous sclerosis, PTEN-related macrocephaly and neurofibromatosis type 1, developmental disorders with high rates of autism, we demonstrated decreased Akt/mTOR pathway in both patients with idiopathic autism and in VPA-exposed rats." (PMID 25627160, 2015). "In humans, dysfunctional mTOR signaling plays an important role in many if not most cancers, as well as in diseases such as tuberous sclerosis complex (TSC, #191100 OMIM) and lymphangiomyelomatosis (LAM, #606690 OMIM)." (PMID 18030348, 2007).
tuberous sclerosis (continued). "If this dual inhibition allows for greater efficacy compared to the first generation of mTOR inhibitors without further significant toxic effects, these new agents may open new possibilities in the treatment of tuberous sclerosis." (PMID 41227201, 2025). "However, mutant models of Tuberous Sclerosis that exhibit hyperactive mTOR do not exhibit the same protein synthesis or mGluR-LTD phenotypes as seen in the Fmr1−/y model, and the role of this pathway in mGluR-LTD in WT is unclear." (PMID 35688821, 2022). "mTOR adaptors were required in leucine-mediated autophagy inhibition and ER stress negatively regulates the AKT/ tuberous sclerosis (TSC)/mTOR pathway to enhance autophagy." (PMID 26636675, 2015). "In this perspective, the mTOR pathway and TSC genes are thought to be affected by epigenetic modifications, and growing evidence suggests that these alterations may contribute to the regulation of gene expression and the diverse clinical features observed in tuberous sclerosis complex." (PMID 40558831, 2025). "BHD syndrome, categorized as a hamartoma disorder, shares phenotypic resemblances with tuberous sclerosis complex (TSC), prompting speculation that BHD may intersect with the pathways signaling through mTOR." (PMID 39201746, 2024). "Cutaneous lesions are one of the hallmarks of tuberous sclerosis complex (TSC), a genetic disease in which mTOR is hyperactivated due to the lack of hamartin or tuberin." (PMID 36077111, 2022). "On the other hand, mammalian target of rapamycin (mTOR) inhibitors have recently been used for tuberous sclerosis (TSC)-related AMLs, and no comparison between the effectiveness of mTOR inhibitors versus prophylactic selective TAE has yet been performed." (PMID 33219488, 2020). "This conclusion is supported by a prior study that assessed PPI in a transgenic mouse model of tuberous sclerosis complex, another model of ASD and mTOR hyperactivation, which similarly reported no deficits in prepulse inhibition between WT and KO mice." (PMID 39822947, 2019). "Rapamycin, a potent inhibitor of mTOR (mammalian target of rapamycin), has been demonstrated to be a potential pharmacological agent against the aberrant mTOR signaling seen in ciliopathies such as polycystic kidney disease (PKD) and tuberous sclerosis complex (TSC)." (PMID 28529994, 2016).
cervical carcinoma (332 papers, 2012 to 2026). A carcinoma arising from either the exocervical squamous epithelium or the endocervical glandular epithelium. "Despite the established importance of Akt-mTOR signaling in cervical cancer, the precise mechanisms underlying its hyperactivation in cervical cancer remain not fully understood." (PMID 40537499, 2025). "A recent study has shown that Gαi3 protein is essential in regulating Akt-mTOR cascade activation in cervical cancer, possibly by associating with multiple receptor tyrosine kinases (RTKs) and non-RTK receptors." (PMID 40537499, 2025). "Conversely, GJB5 overexpression was associated with enhanced Akt-mTOR signaling in primary human cervical cancer cells." (PMID 40537499, 2025). "We performed an AMPK knock-down using AMPK-targeted siRNAs and mTOR inhibition with rapamycin to investigate the molecular mechanisms underlying the effect of metformin in cervical cancer cell lines." (PMID 39026155, 2024). "For example, the exosome-mediated PI3k/Akt/mTOR signaling pathway has been implicated in cervical cancer." (PMID 38627727, 2024). "As an example, high expression of the mTOR protein, an important protein in the regulation of cell proliferation and metabolism, was found to be associated with poor prognosis in cervical cancer treated with radiotherapy." (PMID 37175568, 2023). "The present study is therefore set out to describe potential associations of mTOR and ER expression in a preclinical cervical cancer model." (PMID 37623437, 2023). "Numerous studies reported that co-treatment of cisplatin and mTOR inhibitors such as rapamycin cause autophagy and induce apoptosis in cisplatin-resistant cervical cancer cell lines." (PMID 37836581, 2023). "In regard to EGFR/PTEN/mTOR-pathway alterations, the literature consistently reports mTOR to be active in cervical cancer and to be a key pathway modulating HPV-associated cell signaling alterations." (PMID 37623437, 2023). "The present study is also the first to describe potential associations between EGFR/PTEN/mTOR-pathway alterations and ER expression levels in cervical cancer." (PMID 37623437, 2023). "PIK3CA and MTOR were the most frequently mutated genes, demonstrating that the PI3K/Akt/mTOR signaling pathway is commonly activated in cervical cancer." (PMID 35205332, 2022). "Overexpressing ADRA2A causes senescence (β-galactosidase staining) in cervical cancer cells by down-regulating PI3K/AKT/mTOR, which is reverted by ADRA2A knockdown." (PMID 36139919, 2022). "PI3K-Akt-mTOR is often dysregulated and overactivated in cervical cancer due to various genetic mutations, including PTEN depletion, PI3KCA mutation and sustained activation or mutation of multiple receptor tyrosine kinases (RTKs) 63-65." (PMID 35541904, 2022). "Similar to various other cancers, the prognosis of cervical cancer patients has been linked to the status of the PI3K/AKT/mTOR pathway." (PMID 31058807, 2019). "This pathway, along with mTOR signaling, has been linked to a range of cancers, including cervical cancer and NETs." (PMID 28042953, 2017). "For example, HPV infection has been associated with the deregulation of the PI3K-Akt-mTOR pathway in invasive cervical carcinomas." (PMID 29083376, 2016). "High expression of mTOR protein was associated with a poor prognosis in cervical cancer treated with radiotherapy." (PMID 24466029, 2014). "Moreover, hyperactivation of Akt-mTOR signaling has been implicated in enhancing resistance to apoptosis, thereby contributing to the aggressive nature of cervical cancer." (PMID 40537499, 2025). "Interestingly, to our knowledge, this is the first study to describe associations between p-mTOR immunostaining expression and impaired survival in recurrent cervical cancer." (PMID 37623437, 2023). "In addition, another article reported that a novel copper nanocomplex inhibited cell proliferation and caused the cell death via the PI3K/AKT/mTOR signaling pathway in cervical cancer cells." (PMID 36761763, 2023).